OR5T2 (olfactory receptor family 5 subfamily T member 2)
Description:
Odorant receptor.
Synonyms: OR11-177
Gene: Protein-coding gene on chromosome 11 (56,231,282 to 56,234,255, reverse strand). Ensembl gene ENSG00000181718.
Subcellular location: Cell membrane
Pathways (Reactome):
Sensory Perception: Expression and translocation of olfactory receptors
Genetic constraint (gnomAD): Loss-of-function variants: 12 observed, 13.7 expected, observed/expected ratio (o/e) 0.88, 90% interval 0.56 to 1.42. The upper end of that interval is the gene's LOEUF score, 1.42, which puts it in group 5 of 6, group 1 being the genes least tolerant of losing a copy. Missense variants: 440 observed, 355.34 expected, observed/expected ratio (o/e) 1.24, 90% interval 1.14 to 1.34. Synonymous variants: 138 observed, 136.05 expected, observed/expected ratio (o/e) 1.01, 90% interval 0.88 to 1.17.
Homologues: Orthologues: chimpanzee OR5T2 (97% identical), dog OR5T2B (81% identical), dog OR5T2 (76% identical), rat Or5t7 (73% identical), mouse Or5t15 (72% identical), mouse Or5t18 (72% identical), rat Olr520 (72% identical), mouse Or5t7 (72% identical), mouse Or5t16 (72% identical), rat Or5t16 (71% identical), rat Olr520 (69% identical), zebrafish adra1ab (16% identical), and 1 more. Paralogues in human: OR5T1 (75% identical), OR5T3 (74% identical), OR13F1 (41% identical), OR56A1 (27% identical), OR56A3 (26% identical), OR56A4 (26% identical), OR56A5 (26% identical), ADRA2A (21% identical), ADRA2B (19% identical), ADRA1B (19% identical), ADRA2C (19% identical), ADRA1A (17% identical), and 6 more.